RBFOX1 (RNA binding fox-1 homolog 1)
Diseases named in the same sentence as RBFOX1 in open-access papers (continued):
Sharing a sentence is not in itself a finding about the gene and the disease.
colon cancer (7 papers, 2013 to 2024). "We identified gain of the 16p13.3 locus and loss of the RBFOX1 gene as candidate biomarkers to predict recurrence in colon cancer; especially in stage II tumours where there is a high medical need for new prognostic markers." (PMID 26222184, 2015). "RBFOX1, the RNA binding fox-1 homolog 1, previously associated with developmental coordination disorder and spinal cerebellar ataxia, has also been linked to tumors like gastric and colon cancers now." (PMID 38167455, 2024). "More interestingly, loss of RBFOX1 is a marker excluding disease recurrence in colon cancer." (PMID 26222184, 2015). "Frequent deletion of RBFOX1 in colon cancer, reported in an earlier study, supports its active role in tumorigenesis." (PMID 24937453, 2014). "RBFOX1 belongs to a family of evolutionarily conserved RNA-binding proteins and regulates tissue-specific alternative splicing: deletion of RBFOX1 has been already reported in colon tumors whereas copy number gain has been recently shown." (PMID 27481518, 2016). "For example, focal deletions of RBFOX1 (16p13 locus) are present in both cancer types, while WWOX (16q24 locus) deletions are only visible for colon cancers." (PMID 24684958, 2014). "Deletion of RBFOX1 has been detected in 35% of MSI and 21% of MSS colon tumours in a previous study, and fluorescence in situ hybridization was performed to confirm the somatic deletion of this locus in four samples." (PMID 23286373, 2013). "The immunohistochemical expression of RBFOX1 in human non-neoplastic colon and colon cancer tissues was assessed." (PMID 23286373, 2013).
myopia (7 papers, 2013 to 2023). "CTNND2 is significantly associated with myopia in an Asian GWAS and RBFOX1 has been associated with myopia in a multi-ethnic cohort and also in a Chinese population-based study." (PMID 27623284, 2016). "Our interaction analysis showed at least two genes (CTNND2 and RBFOX1) that have been previously associated with myopia, and are also associated with glaucoma in our datasets." (PMID 27623284, 2016). "Importantly, polymorphisms at both RGR and RBFOX1 have been previously reported to be associated with refractive error and myopia." (PMID 37351342, 2023). "These vQTLs are strong candidates for having either GxE or GxG interaction effects and, indeed, genetic variants located near the GJD2, LAMA2, RBFOX1, KCNQ5 and LRRC4C genes were associated with a progressively increasing risk of myopia as the number of years of schooling rose." (PMID 36395078, 2022). "The current work brings the number of independently replicated gene-by-education interactions for myopia to 3 (ZMAT4, GJD2 and RBFOX1)." (PMID 36395078, 2022).
mental disorder (6 papers, 2015 to 2023). A disease that has its basis in the disruption of mental process. "In line with this strong evidence that genetically driven variation of RBFOX1 expression is associated with mental disorders, we synthesised knowledge of brain expression of RBFOX1 from existing studies on post-mortem brain samples." (PMID 35948661, 2022). "RBFOX1 alterations were also found to be associated with other diseases, like non-small-cell lung cancer, refractive error of the eye, mental disorders and neurodevelopmental disorders." (PMID 26222184, 2015). "It must be considered that genetic variants in RBFOX1 with small effect sizes in a polygenic scenario interact with many other variants to increase the risk towards mental disorders in a quasi-stochastic manner, probably explaining the broad psychopathological phenotype." (PMID 35948661, 2022). "Taken together, common genetic variation in RBFOX1 is robustly associated with a variety of mental disorders and behavioural traits, while rare genetic variation and reduced brain expression appear most strongly linked to neurodevelopmental disorders with onset in childhood and adolescence." (PMID 35948661, 2022). "Finally, the mature stage T5 was enriched for synaptic signaling genes (FDR = 5 × 10–16; e.g., CADPS2 and SNAP25) and regulation of membrane potential (FDR = 3 × 10–11; e.g., RIMS1 and SCN2A), and was most specifically marked by RBFOX1, an RNA-binding protein implicated in many mental disorders." (PMID 36865235, 2023). "We speculate that age-induced hypermethylation might be related to PGC-1α dysfunction, at least in part, resulting in insulin resistance development in children of aged father, and that RBFOX1 dysfunction is implicated in the higher risk of mental disorders of children of older fathers." (PMID 33317634, 2020). "Studying the pleiotropic nature of RBFOX1 can profoundly enhance our understanding of mental disorder vulnerability." (PMID 35948661, 2022). "To delineate the genetic contribution of RBFOX1 to mental disorders, we comprehensively data-mined and synthesised large-scale datasets on common and rare genetic variations in psychiatric disorders and traits." (PMID 35948661, 2022). "Abnormalities in RBFOX1, which is also known as A2BP1, have been associated with mental disorders." (PMID 36986626, 2023). "However, given the decreased expression of RBFOX1 observed in post-mortem studies of ASD and SCZ patients, and the observed over-abundance of RBFOX1 CNV-deletions in (early-onset) mental disorders, we reasoned that loss of RBFOX1 function might underlie at least part of the observed associations." (PMID 35948661, 2022).
spinocerebellar ataxia type 2 (6 papers, 2011 to 2023). A subtype of type I autosomal dominant cerebellar ataxia (ADCA type I) characterized by truncal ataxia, dysarthria, slowed saccades and less commonly ophthalmoparesis and chorea. "RBFOX1 was initially identified as a binding partner of the brain-specific protein ATXN2, causing spinocerebellar ataxia 2 (SCA2) when the CAG repeats in this gene are expanded." (PMID 23822903, 2013). "Although many genes exhibited high editing rate in terms of number of events per locus, RBFOX1 appeared the most edited comprising 142 Alu elements and coding for a RNA-binding protein able to interact with the ataxin-2 which is involved in the familial form of spinocerebellar ataxia type 2 (SCA2)." (PMID 26449202, 2015). "It is thought that RBFOX1 might contribute to the restricted pathology of spinocerebellar ataxia type 2 (SCA2)." (PMID 23028291, 2012).
depression (5 papers, 2022 to 2025). "Recently, the serum levels of RBFOX1, along with transcription factor 4 (TCF4), have been proposed as potential biomarkers for depression due to their substantially increased levels in unmedicated patients with MDD." (PMID 38399469, 2024).
glioblastoma (5 papers, 2014 to 2023). The most malignant astrocytic tumor (WHO grade IV). "MBNL proteins regulate the splicing of tau alternative exon 2, and we find that ectopic expression of RBFOX1 can partially repress the splicing aberration of tau exon 2 induced in T98 glioblastoma cells by transfecting the CUG repeat expression vector DT960." (PMID 25211016, 2014). "Additionally, RBFOX1, like many splicing factors, also has roles in the stabilisation of mRNA by binding to 3′UTR regions, and its loss correlates with poor glioblastoma (GBM) patient survival." (PMID 37924098, 2023).
Parkinson disease (5 papers, 2019 to 2025). A progressive degenerative disorder of the central nervous system characterized by loss of dopamine producing neurons in the substantia nigra and the presence of Lewy bodies in the substantia nigra and locus coeruleus. "Rbfox1 has been associated with neurodevelopmental and neurological conditions as well as age-related neurodegenerative diseases such as Alzheimer’s and Parkinson’s." (PMID 36359797, 2022). "Recent studies also implicate Rbfox proteins, particularly Rbfox1, in the pathogenesis of age-related neurodegenerative diseases such as Alzheimer’s and Parkinson’s diseases." (PMID 36359797, 2022). "For example, it has been reported that neurons derived from iPSCs of Parkinson's disease (PD) patients have elevated RBFOX1 levels." (PMID 31429825, 2019).
Anxiety (4 papers, 2015 to 2025). Intense feelings of nervousness, tension, or panic often arise in response to interpersonal stresses. "Our analyses suggest an involvement of the RBFOX1 gene in the development of anxiety-related conditions such as GAD." (PMID 26274327, 2015). "While we cannot yet finally determine the functional consequences of RBFOX1 genetic variation in humans, combining data from human and rodent experiments may suggest an increase in expression in MDD, anxiety, and (reactive) aggression." (PMID 35948661, 2022).
breast cancer (4 papers, 2015 to 2024). A primary or metastatic malignant neoplasm involving the breast. "To identify transcripts whose AS is likely to play a functional role in promoting EMT, we assessed which QKI and RBFOX1-regulated AS events were also associated with an EMT gene signature across a panel of breast cancer cell lines from the Cancer Cell Line Encyclopedia (CCLE)." (PMID 30059005, 2018). "Here, we found that QKI and RBFOX1 regulate the splicing of an exon in the actin-binding protein FLNB to regulate the EMT in breast cancer." (PMID 30059005, 2018). "Another example is the gene FLNB whose exon 30 was found to be skipped in the majority of tumors, which is consistent with previous findings that the skipping of this exon induces EMT, is associated with basal-like breast cancer, and is regulated by the RNA binding proteins QKI and RBFOX1." (PMID 38674106, 2024). "Among all the common targets of QKI and RBFOX1, we found that CD44 (IC:0.857, p value:<6.59e-07) and FLNB (IC:0.848, p value:<6.59e-07) scored as the top two genes that most strongly associated with the EMT signature in breast cancer cell lines." (PMID 30059005, 2018). "In addition, QKI and RBFOX1 overexpression also significantly increased the CD44-high cell populations in two additional breast cancer cell lines (MCF7 and ZR75-1)." (PMID 30059005, 2018). "Since mesenchymal and stem-like cell features are enriched in basal-like breast cancer, we examined whether the splicing of FLNB and the expression of QKI or RBFOX1 were associated with the basal-like subtype in TCGA Breast Invasive Carcinoma (BRCA) samples." (PMID 30059005, 2018). "We found several targets of QKI and RBFOX1, including FLNB, SLK, USO1, ENAH, ESYT2, NUMB and ARHGEF1, to be among the most differentially spliced genes in basal B breast cancer cell lines." (PMID 30059005, 2018).
diabetes (4 papers, 2016 to 2026). "Since Rbfox1 expression was also reduced in the hypertensive arteries, we questioned whether the decreased Rbfox1 in diabetic arteries was due to diabetic hyperglycemia or diabetes-associated hypertension." (PMID 38575795, 2024). "We confirmed that circRbfox1 remarkably upregulated in T13-L2 dorsal root ganglions in rats with diabetes, and could interact with the RNA-binding protein HuC to promote its transition from the cytosol into the nucleus to promote the translation level of RBFOX1." (PMID 42047689, 2026). "Unexpectedly, the arteries from the patients with diabetes showed increased Rbfox1 expression in comparison to those from nondiabetic patients." (PMID 38575795, 2024).
glioma (4 papers, 2008 to 2024). A benign or malignant brain and spinal cord tumor that arises from glial cells (astrocytes, oligodendrocytes, ependymal cells). "Loss of RBFOX1 function promotes gliomagenesis, and low RBFOX1 expression in glioma tissues is associated with poor survival." (PMID 39387520, 2024). "Of the 11 candidate susceptibility regions, two regions were consistently associated with glioma risk across multiple studies and methods, 16p13.3 an intronic region of the RBFOX1 gene, and 1p36.21 containing the genes PDPN and PRDM2." (PMID 39387520, 2024). "The variant rs2346609 is an intron variant of the RBFOX1 gene and is significantly associated with female glioma susceptibility (OR = 1.24; P = 3.21 × 10−7)." (PMID 39387520, 2024). "Mutated RBFOX1 contributes to the aggressive malignant properties of glioma." (PMID 35887658, 2022). "The 16p13.3 region contains the RNA binding fox-1 homolog 1 (RBFOX1) gene and is associated with all-glioma female risk." (PMID 39387520, 2024). "Two of the 11 regions, 16p13.3 containing RBFOX1 and 1p36.21 containing PRDM2, were significantly associated with female and male glioma risk respectively, based on the results of the meta-analysis." (PMID 39387520, 2024). "RBFOX1 also contributes to the aggressive malignant properties of glioma and regulates the blood–tumor barrier to increase permeability in glioma, eventually resulting in a lower concentration of antineoplastic medication in brain tumors." (PMID 35887658, 2022). "The GBJ set-based analysis of the meta-analysis results found two of the 11 regions (16p13.3 containing RBFOX1 and 1p36.21 containing PRDM2) were significantly associated with female and male glioma risks, respectively, after adjusting for multiple testing (P16p13.3 = 0.003; P1p36.21 = 0.002)." (PMID 39387520, 2024). "RBFOX1 further regulates the blood–tumor barrier to increase permeability in the glioma and may serve as a target to provide a higher concentration of antineoplastic medication in brain cancer." (PMID 35887658, 2022).
Rolandic epilepsy (4 papers, 2013 to 2022). "In this study, we explored if structural microdeletions and exonic sequence variations in RBFOX1, RBFOX2, RBFOX3 confer susceptibility to rolandic epilepsy (RE), a common idiopathic focal childhood epilepsy." (PMID 24039908, 2013).
Ataxia (3 papers, 2012 to 2025). Ataxia refers to impaired coordination of voluntary muscle movement. "While the isolated knockout of RBFOX1 or RBFOX2 causes minimal cortical malformation due to functional redundancy, RBFOX1 KO mice exhibit increased seizure susceptibility, and RBFOX2 KO leads to cerebellar defects and ataxia." (PMID 41303558, 2025). "RBFOX1 physically interacts with the c-terminus of ATXN2, another autosomal dominant gene causing cerebellar ataxia." (PMID 23028291, 2012).
cardiomyopathy (3 papers, 2015 to 2023). A disease of the heart muscle or myocardium proper. "To date, Rbfox1/2 was reported to be crucial in cardiac development and different cardiomyopathies via regulation of serial splicing events, indicating a plausible role in the regulation of alternative exon 33 of CaV1.2 calcium channels in the heart." (PMID 28949795, 2018). "In this follow-up study of our previous work, we measured Rbfox1/2 mRNA levels in human failing and non-failing heart samples, in order to explore the possible association between the expressions of Rbfox and exon 33 of CaV1.2 in cardiomyopathies." (PMID 28949795, 2018). "Therefore, induction of Rbfox1 expression might have some beneficial effects on the cardiomyopathies." (PMID 28949795, 2018).
colorectal adenoma (3 papers, 2013 to 2019). An adenoma that arises from the colon or rectum. "Single nucleotide polymorphisms were found in RBFOX1 in the region proximal to our SRO in colorectal adenomas." (PMID 26222184, 2015).
developmental delay (3 papers, 2015 to 2024). "With regard to functional relevance, A2BP1, also known as RBFOX1, codes for a neuron-specific splicing factor associated with synaptic transmission, neurodevelopment, and developmental delay." (PMID 26056561, 2015).
generalized epilepsies (3 papers, 2013 to 2022). "Partial deletions of the gene encoding the neuronal splicing regulator RBFOX1 have been reported in a range of neurodevelopmental diseases, including idiopathic generalized epilepsy." (PMID 24039908, 2013). "Recently, we have shown in 1408 idiopathic generalized epilepsy (IGE) patients and 2256 population controls that deletions affecting 5′ located exons of RBFOX1 are significantly enriched in IGE cases compared to population matched controls." (PMID 24039908, 2013). "A previous study of 1408 unrelated individuals with idiopathic generalized epilepsy revealed exon-removing RBFOX1 microdeletions in five patients, whereas none was found in 2256 ethnically matched controls." (PMID 24039908, 2013).
Stroke (3 papers, 2015 to 2024). Sudden impairment of blood flow to a part of the brain due to occlusion or rupture of an artery to the brain. "Taken together, these results suggest that CRTC1 deletion and miR-132/212 knockdown both aggravate post-stroke neuronal damage and upregulate RBFox-1 in neurons." (PMID 34880207, 2021). "Here, we show, for the first time, changes in RBFox-1 after stroke, both in vivo and in vitro, and the role of CRTC1-miR-132/212 in these changes." (PMID 34880207, 2021). "Another hub gene in our analyses is RBFOX1, which, in addition to having a role in amyloid accumulation mediates ischemic damage by enhancing neuronal survival and BBB integrity after stroke." (PMID 39046104, 2024).
amyloid (2 papers, 2022 to 2025). "AD-associated risk genes, including APP, PICALM, and RBFOX1, were positively correlated with plasma cells, activated CD4+ T cells, and Tregs, linking amyloid-related pathways to adaptive immune activation." (PMID 41567547, 2025). "On the other hand, RBFOX1—an RNA-binding protein found as top signal that is a recent GWAS for amyloid load in AD and involved in amyloid clearance —is a non-synergistic DEG." (PMID 35681503, 2022).
cerebral infarction (2 papers, 2021 to 2022). An ischemic condition of the brain, producing a persistent focal neurological deficit in the area of distribution of the cerebral arteries. "To date, there are no published reports of RBFox-1-mediated splicing changes after cerebral infarction." (PMID 34880207, 2021).
cognitive decline (2 papers, 2025). "Reduced expression of RBFOX1 has been shown to occur with higher Aβ burden and cognitive decline." (PMID 39868232, 2025).
colorectal cancer (2 papers, 2013 to 2024). A primary or metastatic malignant neoplasm that affects the colon or rectum. "For example, in the study of colorectal cancer in British Bangladeshis, RBFOX1 deletion was associated with high prevalence, early onset, and frequent mucous tissue types of colorectal cancer." (PMID 38167455, 2024).
COVID-19 (2 papers, 2023 to 2025). A disease caused by infection with severe acute respiratory syndrome coronavirus 2. "At that time, only for two genes, LUZP2 and RBFOX1, both COVID-19- and AD-associated SNPs were found at the genome-wide significance level p ≤ 5 × 10−8." (PMID 37927339, 2023). "In our study, minor alleles of RBFOX1 variants were associated with a lower probability of developing radiological affectation, thus providing evidence for the role of RBFOX1 in corticoid and the immunomodulator response in COVID-19 patients." (PMID 40149530, 2025). "In addition, four genes belonging to the first subgroup: DLG2, MTMR2, RBFOX1, and DCC, are involved in synapse formation and signal transduction, what may indicate deregulation of these processes in the development of COVID-19 and AD-associated cognitive impairment." (PMID 37927339, 2023).
cyst (2 papers, 2023). A sac-like closed membranous structure that may be empty or contain fluid or amorphous material. "Consistent with this hypothesis, loss of Rbfox1 and ectopic expression of pum blocks cystocytes differentiation and results in germ-line tumors due to cyst breakdown and dedifferentiation of cystocytes into single mitotically proliferating cells." (PMID 37367475, 2023). "In the CB, expression of Bag of marbles (Bam) promotes the progression from CB to an 8-cell cyst stage where expression of RNA-binding Fox protein 1 (Rbfox1) and Bruno 1 (Bru1) are required to specify an oocyte." (PMID 37343092, 2023). "However, in the eight-cell cyst, a switch from mitotic to meiotic programming is induced by the expression of RNA-binding Fox protein 1 (Rbfox1)." (PMID 37367475, 2023).